INS (insulin)
Diseases named in the same sentence as INS in open-access papers (continued):
Sharing a sentence is not in itself a finding about the gene and the disease.
prediabetes (continued). "In our study, animals of the HFHFrD group showed elevated blood glucose, serum insulin, and HOMA-IR values, indicating development of a prediabetes-like state." (PMID 35726330, 2022). "Our results suggest new beneficial effects of CaVγ4 with the potential to preclude the development of prediabetes-related IFG and IGT through its influence on insulin secretion capability in islets." (PMID 35453520, 2022). "A direct relationship has been demonstrated between impaired insulin-stimulated myocardial glucose uptake and reduced peripheral insulin sensitivity in patients with T2DM and in individuals with prediabetes." (PMID 35845046, 2022). "Significant associations were found between TG levels and TG/HDL ratio and insulin/HOMA-IR/HOMA-β in both the Finnish and Chinese prediabetes (all p < 0.05–0.001)." (PMID 35325446, 2022). "Specifically, our study recruited prediabetes cohort which provides new insights into the role of endogenous GLP-1 levels on glucose metabolism, insulin sensitivity and beta cell function in the presence of DPP-IV inhibition." (PMID 36267570, 2022). "Using a highly controlled feeding study, we compared the effects of a high vs. low GI diet in the setting of relative weight stability on insulin sensitivity and β-cell function, assessed during an MTT in adults with prediabetes." (PMID 35215537, 2022). "Fasting insulin is considered part of the clinical definition of T2DM and is an effective clinical tool for predicting prediabetes." (PMID 36589843, 2022). "Even though the myocardial blood flow and myocardial flow reserve were similar, individuals with prediabetes and newly diagnosed T2DM had-despite of elevated levels of glucose and insulin-a decreased myocardial glucose uptake compared to NGM." (PMID 34827678, 2021). "In fact, a recent study in postmenopausal, overweight women with prediabetes, demonstrated that 10 weeks of NMN supplementation increases skeletal muscle insulin signaling, insulin sensitivity, and muscle remodeling." (PMID 34660673, 2021). "As for the dysglycemic group, the groups with prediabetes or IGT had lower insulin sensitivity, disposition index, and insulin clearance, but similar insulin secretion compared to the group with normal glucose tolerance." (PMID 34206745, 2021). "OGIS index has been reported to be a better surrogate marker of insulin sensitivity in comparison with other indices such as Matsuda index, QUICKI, and HOMA-IR, especially in subjects with prediabetes." (PMID 33457118, 2020). "Abnormalities in β-cell function are present in prediabetes and T2DM, whereas insulin sensitivity already declines decades before T2DM onset." (PMID 33096658, 2020). "Pubertal obese children with prediabetes HbA1c also had lower insulin sensitivity (lower WBISI and QUICKI, but higher HOMA-IR), but higher total insulin secretion (higher AUC of insulin) as a compensatory mechanism, than those with normal HbA1c." (PMID 33224197, 2020). "We additionally assessed cold-induced changes in ANGPTL levels in relation to delta glucose, delta insulin levels, as well as HOMA-IR under insulin resistant conditions (i.e., in the cohort of middle-aged men with overweight and prediabetes)." (PMID 31416197, 2019). "At the early stage of prediabetes, the OGTT results demonstrated that the insulin exhaustion appeared in the second phase of insulin release." (PMID 30975975, 2019). "A previous study has shown that PIAS1 is downregulated in white adipose tissue of mice with prediabetes, whereas overexpression of PIAS improved insulin sensitivity and visceral adipose tissue inflammation." (PMID 31906225, 2019). "Prediabetes and T2DM remission and concomitant HbA1c improvements are related to better insulin sensitivity and glucose metabolism that influence weight-dependent (body weight loss) and independent (hormonal glucagon-like peptide 1) pathways." (PMID 28822064, 2018).
prediabetes (continued). "All the markers of IR, including fasting insulin, HOMA-IR, BMI, WC, SBP, FPG levels were significantly higher in subjects with T2DM and prediabetes compared to NGT subjects in our study population." (PMID 30200612, 2018). "We followed up this work in 2013 to examine the inter-individual variability in the therapeutic response of blood glucose control in 105 older obese individuals with prediabetes or T2DM, excluding those treated with insulin." (PMID 30061841, 2018). "As expected, subjects included in the prediabetes and T2DM groups had significantly higher BMI, waist circumference, WHR, fasting glucose, and fasting serum insulin levels compared to those in the NGT group." (PMID 29707577, 2018). "While both insulin-stimulated LV GU and RV GU seemed to be lower in subjects with T2DM or prediabetes in the present study compared to the healthy subjects at the baseline, after the training the difference diminished due to reduced GU of the healthy subjects." (PMID 28874821, 2017). "Participants in the prediabetes, T2DM, and FDRs groups had higher levels of FPG, fasting insulin, and HOMA-IR than the NGT group." (PMID 28596534, 2017). "Indices of insulin secretion and action from the OGTT were only calculated in healthy controls, prediabetes and T2D subjects." (PMID 27558530, 2016). "The prediabetes group consisted of both IFG and IGT which have been reported to have different etiologies with respect to basal insulin secretion and resistance of glucose production to suppression by insulin." (PMID 24086336, 2013). "Patients who did not use insulin and were in the prediabetes category answered the questions based on their current knowledge about insulin treatment." (PMID 41736002, 2026). "In prediabetes, it has been observed that TSH concentration may increase, potentially due to the interplay between insulin resistance and the hypothalamic–pituitary–thyroid (HPT) axis." (PMID 40076791, 2025). "We tested the hypothesis that short‐term exercise would raise neuronal insulin signaling and pro‐BDNF in neuronal extracellular vesicles (nEVs) in prediabetes." (PMID 39421964, 2025). "Of note, 90% of patients without manifest T2D were insulin resistant, and more than half of those patients had prediabetes (impaired fasting glucose)." (PMID 39943818, 2025). "IGF-1 levels were positively correlated with both insulin and testosterone levels in women with prediabetes (r = 0.265, p = 0.008; r = 0.435, p < 0.001, respectively) but not in those without prediabetes." (PMID 41384021, 2025). "In contrast, traditional markers like HOMA-IR showed limited utility in prediabetes (AUC: 0.665), likely due to their reliance on static glucose-insulin measurements rather than dynamic lipid-glucose interactions." (PMID 41430716, 2025). "For instance, it is unclear how people in our study matched on age, sex, BMI, and fitness to adults without prediabetes would compare in terms of nEV insulin signaling before and after exercise training." (PMID 39421964, 2025). "This is in line with our findings, except the insulin functionality, which was not discussed in our focus groups since our e-health program primarily targets lifestyle intervention in people with prediabetes and T2D not using insulin." (PMID 40029895, 2025). "JLD may help improve glycemic control, insulin resistance, and lipid profiles in patients with T2DM and prediabetes." (PMID 41334442, 2025). "As prediabetes is often overlooked, it progresses toward symptomatic T2DM after β-cell failure, when pancreatic islets are unable to compensate for increasing systemic insulin demands." (PMID 40775511, 2025). "The NDPKB−/− mice were glucose intolerant, yet insulin secretion and ITT remained unaltered, suggesting an early stage of prediabetes in which insulin sensitivity may still be preserved during the ITT, even though glucose metabolism is impaired during the GTT." (PMID 39985023, 2025).
prediabetes (continued). "Although IGF-1 may not represent a primary etiological driver, its contribution to androgen biosynthesis underscores the importance of targeting insulin and IGF-1 pathways to prevent the reproductive and metabolic complications of prediabetes." (PMID 41384021, 2025). "On the other hand, an insulin blood test is not a frequently requested exam by clinicians for prediabetes diagnosis, and it does not lend itself as well to large epidemiological studies, where a quick and simple insulin assessment is important." (PMID 40556956, 2025). "In previous reports from the POP-ABC study, higher disposition index at baseline was a stronger predictor of nonprogression from normoglycemia to prediabetes compared with insulin sensitivity or insulin secretion alone." (PMID 41163811, 2025). "However, the HP diet exhibited a higher prediabetes remission rate, possibly due to increased GLP-1 and GIP levels, enhancing insulin secretion and glucose handling." (PMID 38255264, 2024). "PD, prediabetes; T, tertile; WC, waist circumference; BMI, body mass index; BF, body fat; FPG, fasting plasma glucose; HbA1c, glycated hemoglobin; SI, serum insulin; TC, total cholesterol, TG, triglycerides; HDL, high-density lipoprotein; LDL, low-density lipoprotein; Vit." (PMID 38800767, 2024). "Yet, clinicians do not routinely measure insulin levels, partly because clinical guidelines do not integrate measures of IR, and other methods for diagnosing prediabetes and T2DM are used." (PMID 38396727, 2024). "Another meta-analysis among subjects with prediabetes, showed no overall improvements in insulin resistance and glycemic control in relation to vitamin D supplementation." (PMID 38956028, 2024). "Another 12-week study found that GOS supplementation selectively increased fecal Bifidobacterium fivefold, but did not significantly affect insulin sensitivity in 44 overweight/obese individuals with prediabetes." (PMID 39458444, 2024). "No sex-related differences in whole-body insulin-stimulated glucose disposal were observed between men and women in prediabetes and diabetic groups." (PMID 38671460, 2024). "Therefore, a prediabetic state that impairs insulin-mediated inhibition of GSK3β by reduced expression of GSK3β-pSer9 may allow pathological activation of GSK3β and tau hyperphosphorylation and contribute to the increased incidence of dementia in people with prediabetes." (PMID 38416718, 2024). "Prediabetes was also associated with high LDL, independent of folate and vitamin D. Poor insulin secretion was high in those with low vitamin B12." (PMID 39055387, 2024). "Incorporation of 20 g of almonds, 30 min before each major meal led to a significant decrease in PPHG (as revealed in OGTT-based study phase) and also improved insulin, C-peptide, glucagon levels, and improved glucose variability and glycemic parameters on CGMS in participants with prediabetes." (PMID 36732571, 2023). "In our study, we found that T2, ADC, FA, and IMAT (%) values correlated positively with key clinical indicators (fasting blood glucose, fasting insulin, OGTT-AUC, and HOMA-IR) in IMAT and muscles, indicating that multimodal MRI can help detect metabolic changes in IMATs in prediabetes subjects." (PMID 37899436, 2023). "After 16 weeks of feeding, HFD-fed mice showed characteristic symptoms of prediabetes, including weight gain, abnormal blood glucose levels, and hyper insulin levels in the serum under non-fasting conditions, compared with STD-fed mice." (PMID 36780539, 2023). "In a study of 490 adults without prediabetes and type 2 DM at baseline and with complete data at follow-up examinations, the glucose, insulin, and 25(OH)D levels were measured at baseline and after four years." (PMID 36820117, 2023). "In fact, the severity of β cell dysfunction is the major determinant of developing T2D rather than prediabetes because insulin resistance is often not different between people with prediabetes and T2D." (PMID 37166995, 2023).
prediabetes (continued). "In individuals with IGT, higher dietary GOS intake was associated with lower body fat and higher insulin sensitivity independent of macronutrients and fibre intake, calling for interventional studies to evaluate the effect of FODMAP intake in prediabetes." (PMID 38140329, 2023). "Indeed, clinical diagnosis of prediabetes or T2DM is mainly based on HbA1c or fasting plasma glucose levels, as insulin resistance testing is practically complex." (PMID 37764732, 2023). "Prediabetes is a heterogeneous disease according to each patient’s response to the OGTT, and the pathophysiologic characteristics of IFG and IGT are considerably different in terms of insulin resistance and insulin secretion." (PMID 37864066, 2023). "(i) It identified glucose metabolism status, i.e., insulin sensitivity and secretion, rather than prediabetes." (PMID 36118835, 2022). "Insulin, either fasting or with an OGTT, is another pathology test that GPs and medical specialists might use when screening and diagnosing prediabetes." (PMID 36411411, 2022). "Overall, the authors concluded that in adults with prediabetes, β-cell function improved independent of exercise intensity, when adjusting for skeletal muscle insulin sensitivity." (PMID 35834023, 2022). "No insulin tests were requested for prediabetes management by any of the participating GPs in four of the 16 years of the study, and the highest proportion of requests was in 2012/13 (3.6% of management occasions, 95% CI: 2.5–6.9%)." (PMID 36411411, 2022). "In the prediabetes group, treatment with linagliptin did not alter fasting and postload serum insulin levels in prediabetes in both the low and high GLP-1 groups." (PMID 36267570, 2022). "The authors of the analysis observed that supplementation with VitD3 did not improve insulin sensitivity or β-cell function in people with prediabetes, but there was benefit among those with very low baseline total 25OHD status." (PMID 36014761, 2022). "We expect weaker correlations between weight loss and the change in insulin secretion (compared to insulin sensitivity), as well as an independent association of low insulin secretion and insulin-resistant NAFLD with the non-remission of prediabetes." (PMID 36432409, 2022). "Inducible adipose tissue-specific and skeletal muscle-specific Munc18c knockout mouse models are needed to investigate target tissue-specific insulin-stimulated GSV translocation and glucose uptake in vivo and to evaluate a candidate therapeutic target for prediabetes and T2D." (PMID 35774142, 2022). "in 60 subjects with prediabetes or T2D, did not improve glycemic control but increased insulin sensitivity." (PMID 35600606, 2022). "We also observed a significant improvement in oral disposition index, a dynamic measure of pancreatic beta cell function that has been adjusted for the influence of prevailing insulin sensitivity level, in the high GLP-1 prediabetes group treated with linagliptin." (PMID 36267570, 2022). "To further explore whether serum metabolic indexes could be affected by β-cell insulin secretion, we divided T2DM and prediabetes patients into subgroups by HOMA-β with the cut-off value of 62.9 for male and 60.6 for female." (PMID 36045734, 2022). "In most patients with prediabetes, a decrease in the GLP-1 concentration was found after glucose challenge, and this was not related to a deficiency in first-stage basal insulin secretion." (PMID 36422091, 2022). "Given the current, and potential uses of these hyperglycaemia-related tests (FBG, HbA1c, OGTT and insulin) and their cost implications, it is important to document pathology referral activity by GPs in Australia within the broader picture of T2DM and prediabetes." (PMID 36411411, 2022). "In our experimental conditions, the insulin response was not altered suggesting a prediabetes status." (PMID 33925459, 2021).
prediabetes (continued). "Although metformin did not reverse the prediabetes, it prevented the decompensation of Chow NRs by reducing hepatic glucose production, sustaining insulin secretion compensation, and protecting β-cells against dysfunction." (PMID 33401592, 2021). "For example, in an individual with prediabetes, HOMA-β may be higher, indicating that insulin secretion is increasing to compensate for higher blood sugar." (PMID 34072554, 2021). "Alongside these, increased CB chemosensitivity, measured by the Dejours test, observed in prediabetes patients is directly correlated with plasma insulin levels and with insulin resistance but not with fasting glycemia." (PMID 32756352, 2020). "In the prediabetes stage, microvascular dysfunction is correlated with the insulin, rather than FPG level." (PMID 32966328, 2020). "Because metformin is advised as a first-line pharmacological agent, we conducted a double-blind, randomized control trial to test the effect of exercise training with and without metformin on insulin sensitivity in people with prediabetes." (PMID 32849302, 2020). "Clinical studies have demonstrated that GLP-1RAs can effectively control blood glucose, induce weight loss, protect pancreatic β-cells, decrease visceral and hepatic fat deposits, and improve overall and hepatic insulin sensitivity in obese patients with T2DM and prediabetes." (PMID 32566685, 2020). "We have further shown that bredemolic acid (BA), a structural isomer of maslinic acid, is able to restore glucose homeostasis in diet-induced prediabetes by improving insulin sensitivity both in presence and absence of dietary intervention." (PMID 32149046, 2020). "Reduced β-cell function (BCF) can be considered as the critical determinant for the development of prediabetes and T2DM because β-cells can compensate for a decreased insulin sensitivity by upregulating insulin secretion and thereby prevent the development of T2DM." (PMID 29525890, 2019). "The primary finding in this study was that CONT and INT exercise for 2 weeks did not increase endothelial function in obese people with prediabetes despite improvements in glucose tolerance and insulin responses to the OGTT." (PMID 31976336, 2019). "Another consideration is that despite individuals with prediabetes having elevated post-prandial glucose and insulin concentrations versus those with NGT, HbA1c was not statistically different between the two groups (P = 0.11)." (PMID 30857250, 2019). "In addition, we did not observe correlations between the cold-induced response in either one of the ANGPTLs and delta glucose, delta insulin levels, or HOMA-IR in the middle-aged men with overweight and prediabetes." (PMID 31416197, 2019). "Oral hypoglycaemic drugs (but not insulin) were also found to have beneficial effects in this review, so the combination of multiple treatments for multiple risk factors in people with T2D may explain why the risks in this group are comparatively lower than prediabetes or MetS." (PMID 30182156, 2018). "Our results support a role for first meal energy intake to influence postprandial glucose and insulin responses in adults with prediabetes, independent of macronutrient composition." (PMID 29882811, 2018). "The adverse effects of low serum vitamin D levels on increasing prediabetes or T2DM risks may be related to its effect on promoting β-cell function and insulin sensitivity." (PMID 29743959, 2018). "Thus, the lower levels of miR-15a that we observed in the patients who develop prediabetes and T2DM suggest that an impairment of stimuli for insulin secretion occurs before the development of T2DM." (PMID 30598522, 2018). "Very recently, a 4-month diet supplemented with 57 g/day of pistachio (50% carbohydrates, 33% fat) modified circulating microRNAs (miR-192 and miR-375) and these changes were positively correlated with plasma glucose, insulin and HOMA-IR in 49 subjects with prediabetes." (PMID 29165404, 2017).